CCR1 (C-C motif chemokine receptor 1)
Diseases named in the same sentence as CCR1 in open-access papers (continued):
Sharing a sentence is not in itself a finding about the gene and the disease.
cancer (continued). "Another pro-cancer property of CCL16 is the induction of angiogenesis, related to the expression of its receptor CCR1 on vascular endothelial cells." (PMID 33182504, 2020). "The picture seems to be more complex in the case of axes including CCL5 and CCL3, and their shared receptors CCR1 and CCR5 in regulating bone remodeling in cancer." (PMID 32582148, 2020). "In short, the collaborative work of CCR1, MMP9, and MMP2 at metastatic sites promotes cancer metastasis." (PMID 31474975, 2019). "Relative CCR1 staining intensity was significantly higher in IDC than their adjacent normal tissues (mean ± SD; normal: 1.669 ± 1.886, Cancer: 5.781 ± 2.513; P < 0.0001 by two-tailed paired t-test, n = 178)." (PMID 29212252, 2017). "Although CCL5 can bind to some chemokine receptors such as CCR1, CCR3 and CCR5, it is unclear which particular receptor is responsible for the pharmacologic CCL5 neutralization that can suppress cancer progression in mouse xenograft models." (PMID 27136535, 2016). "Critical involvement of CCR1, MMP9 and MMP2 was verified experimentally using gene knockout mice lacking these proteins, which suggested possible therapeutic intervention of cancer progression by targeting these molecules." (PMID 25326065, 2014). "In summary, we have identified myeloid cells that express CCR1, MMP9 and MMP2 to promote cancer metastasis." (PMID 25326065, 2014). "We also found that reducing cancer cell expression of the CCL7 receptor, CCR1, also reduced fibroblast-induced proliferation." (PMID 24068959, 2013). "However, studies using double-knockout mice for CCR1 and CXCR2 remain unexplored in cancer research." (PMID 38750114, 2024). "Furthermore, CD276 expression was significantly correlated with chemokine receptor genes, including CCR1 [chemokine (C-C motif) receptor 1], in the KICH, LGG, LIHC and THCA cancer types." (PMID 36717836, 2023). "In addition, SERPINH1 also related to their receptors in pan-cancer, such as CXCR4, CCR1, and CCR10." (PMID 36105106, 2022). "In addition, we can find that its expression positively related to multiple chemokines receptors in pan-cancer, such as CXCR4, CCR1, and CCR10." (PMID 36105106, 2022). "Results of external validation in eRic database showed the specific chromatin localization and target genes of the four key DEeRNAs (CCR1, CD3D, PHLDA1, and RASD1), as well as potential drugs that may target these DEeRNAs in different cancers." (PMID 36092920, 2022). "CCL5 receptors include CCR1, CCR3 and CCR5, while in cancer research CCR5 is the main receptor." (PMID 29088737, 2017). "For example, CCR1, IL1RAP, CCL22 and CSF1 are all involved in metastatic dissemination, and their aberrant expression correlates with leukocyte infiltration and aggressive phenotype in various cancer types." (PMID 26536459, 2015). "Additionally, FJX1 expression was significantly and positively correlated with immunosuppressive genes (TGFB1 and IL-10), chemokines (CCR1 and CCR5), chemokines receptors (CCL2 and CXCL5), and immunosuppressive pathway-related genes (TFGB1 and WNT1), in most TCGA cancers." (PMID 37324001, 2023). "However, we found that CCL5-activated CCR1 preferentially recruited Gαi, which rarely affects the ERK kinase pathway, and that it inhibited STAT3 phosphorylation by upregulating ITPR3, which is essential for both immune activation and cancer pathogenesis." (PMID 36317881, 2022). "The results revealed that none of the CCL5, CCR1, CCR3 and CCR5 was expressed in the ovarian paracancerous tissues, whereas all these molecules were expressed in both primary cancer tissues and metastatic tissues." (PMID 25788271, 2015). "However, even with these limitations, many of the findings discussed have been validated by the fact that the same chemokine systems appear to be involved in mediating bone metastasis regardless of the cancer of origin, in particular CCL2/CCR2, CCL3/CCR1, IL-8/CXCR1, and CXCL12/CXCR4." (PMID 29930538, 2018).
infection (78 papers, 2004 to 2026). The state of being infected such as from the introduction of a foreign agent such as serum, vaccine, antigenic substance or organism. "Infection associated receptor encoding genes include CCR1 (encoding a receptor for CCL5), CRLF2 (cytokine receptor like factor 2), IL10RA, TLR2, CD2, CD48 and IL7R." (PMID 35061738, 2022). "CCR1 infection typically results in plant lethality for these alleles, and the ubiquitous nature of this pathogen makes them difficult to propagate in the field." (PMID 30332488, 2018). "This was not the case with plants carrying only the null allele; they remained uniformly susceptible to CCR1 infection even at maturity." (PMID 30332488, 2018). "The C-C Chemokine Receptor 1 (CCR1), encoded by the CCR1 gene, has been shown to be widely expressed in immune cells and it was associated with the maintenance of chemokine gradients during infection." (PMID 29238336, 2017). "A mouse study that exposed animals to C. difficile toxin A implicated CCL5 (and its receptor, CCR1) as an important mediator of acute intestinal inflammation during infection." (PMID 24643077, 2014). "Next, we aimed to exclude the possibility that decreased accumulation of neutrophils in Ccr1−/− kidneys late after infection was caused by decreased expression of other neutrophil-targeted chemoattractant receptors and ligands and/or adhesion molecules in Ccr1−/− kidneys." (PMID 22916017, 2012). "Last, we sought to determine whether the higher Ccr1 expression seen on kidney neutrophils late after infection is associated with an increased ability of neutrophils to cause tissue injury." (PMID 22916017, 2012). "Thus, broad inhibition of chemokine receptors may compromise immune function, increasing susceptibility to infections or impairing wound healing—as seen in models of CCR1 or CCR2 antagonism during viral infection." (PMID 40859641, 2025). "The chemokine CCL3 and its receptor CCR1 were upregulated 10.5- and two-fold, respectively, by the infection." (PMID 41398915, 2025). "By bonding with particular chemokines, such as CCL3, CCL4, CCL5, CCR1 facilitates cell chemotaxis, directing immune cell migration towards inflammatory or infection sites, a function vital for initiating and modulating immune responses." (PMID 39931101, 2024). "For example, CCL3, which is highly upregulated during infection with C. violaceum, can bind to CCR1 (along with several other chemokines), and CCL3 can also bind to CCR5 (again, along with several other chemokines)." (PMID 38352492, 2024). "In fact, in vivo treatment with Met-RANTES, an antagonist of CCR1 and CCR5, resulted in animals being more susceptible to the infection and in an increase in lesion size." (PMID 34832536, 2021). "Downregulation of CCR1 expression has been reported after infection with Leishmania infantum or coronavirus." (PMID 33509198, 2021). "We performed RT-PCR to detect CCR1 expression after JEV infection, and found that CCR1 messenger RNA (mRNA) levels were significantly decreased at 24 and 36 h post-infection." (PMID 33509198, 2021). "CCR1, a receptor involved in chemotaxis of immune cells at the site of inflammation, was upregulated after apical infection." (PMID 32872518, 2020). "In our context, basolateral infection of HIBCPP cells leads to a lower expression of CCR1 compared to apical infection." (PMID 32872518, 2020). "On the other hand, we noticed a relative downregulation of many important genes upon basolateral infection compared to apical, CCR1, ITGα5 and IFNλ-1, -2 and -3." (PMID 32872518, 2020). "Instead, infection with candidalysin-deficient strains resulted in decreased CCL3 levels, the ligand for CCR1, and decreased renal pelvis damage and neutrophil-mediated immunopathology." (PMID 31401652, 2019). "The nature of molecular changes in the mutant alleles of Hm1 generated by mutagenesis and their respective disease/resistance phenotypes to infection by CCR1 at maturity." (PMID 30332488, 2018).
infection (continued). "We found that in the early stage of infection by P. brassicae, CCR1 and CCoAOMT were up-regulated and CAD5 was down-regulated at 24 hpi, while CAD6 and CAD9 were up-regulated at 48 hpi." (PMID 28484434, 2017). "Accordingly, the expression of the receptors for Ccl3 and Cxcl12, Ccr1 and Cxcr4, respectively, were significantly upregulated by the interaction of low diet and infection (p < 0.05)." (PMID 28397794, 2017). "The amount of VEGFR2, CCR1, and EpCAM protein in pRNAT-shVCE transfected Huh7 cells also decreased greatly 24, 48, and 72 hours after infection." (PMID 27221035, 2016). "In this study, the expression levels of the genes encoding IL-8, CXCL2, and chemokine receptor CCR1 were upregulated during PCMV infection, suggesting that IL-8 exerts an effect similar to its effect during infection by other Herpesviridae family viruses." (PMID 25423176, 2014). "To characterize the cellular composition of the abscesses seen in Ccr1+/+ and Ccr1−/− kidneys post-infection, we performed immunohistochemistry (IHC) using 7/4, a marker on the surface of mouse neutrophils and monocytes/macrophages." (PMID 22916017, 2012). "We next determined the levels of the Ccr1 agonists Ccl3, Ccl5, Ccl6, Ccl7, Ccl8 and Ccl9 in Ccr1+/+ and Ccr1−/− kidneys after infection." (PMID 22916017, 2012). "Further, when MACS-sorted neutrophils from Ccr1+/+ kidneys were tested, Ccr1 mRNA was significantly greater in the late phase (days 6 and 9 post-infection) relative to the early phase (day 3 post-infection) (P<0.05)." (PMID 22916017, 2012). "In particular, the percentage of Ccr1+ kidney neutrophils increased from ∼20–30% on day 3 post-infection to ≥60% on day 9 post-infection (P<0.0001)." (PMID 22916017, 2012). "Third, the decreased kidney tissue injury was associated with a large and selective reduction in neutrophil accumulation in Ccr1−/− kidneys after infection." (PMID 22916017, 2012). "The second important new question that arises from our study pertains to the chemotactic factors responsible for neutrophil recruitment in the kidney during the first 6 days after infection, when Ccr1 is dispensable for neutrophil accumulation in the kidney." (PMID 22916017, 2012). "Ccr1 induction was greatest in the kidney, peaking at a >100-fold increase over the uninfected state on day 9 post-infection." (PMID 22916017, 2012). "Comparing the mock and SARS-CoV infected adult DCs, there was moderate induction of CCR-1, CCR-3, CCR-5 and CCR-7 at both 3 h and 9 h post infection but only that observed for CCR-1 and CCR-5 reached statistical significance." (PMID 19505311, 2009). "Early infection triggered a monocyte-specific antiviral response marked by changes in the expression of genes associated with lipid metabolism (LIPA, lysosomal acid lipase) and chemotaxis (CCR1 and CCR2)." (PMID 41332545, 2025). "Interestingly, downregulated genes also carried roles seen in systemic inflammatory response and susceptibility to infection, including TNSF12, CCR1, and CCR2." (PMID 39666613, 2024). "In contrast, some paired ligands and receptors, such as ANXA1_FPR1, C5AR1_RPS19, CCL5_CCR1, and PTPRC_MRC1, were significantly activated after infection, which may mediate the communication among T cells and myeloid cells." (PMID 37087411, 2023). "Infection led to robust induction of chemokine and interleukin genes, including Il1b, Il6, Ccl2, Ccl3, Ccl4, Ccl7, Cxcl1, Cxcl2, Cxcl5, Cxcl9, and Cxcl10, and related receptor genes, including Ccr1, Ccr4, Ccr5, Ccr5, Ccr7, Cxcr2, Cxcr5, Il1r2, and Il1rn." (PMID 35487885, 2022). "Since lncRNA-SUSAJ1 suppresses JEV proliferation, CCR1 may play a positive role in promoting JEV proliferation post-infection." (PMID 33509198, 2021). "RT-PCR results showed that CCR1 inhibitor ZK811752 could suppress the JEV mRNA levels at 48 h post-infection." (PMID 33509198, 2021). "RT-PCR results showed that CCR1 knockdown could suppress the JEV mRNA levels at 48 h post-infection." (PMID 33509198, 2021).
infection (continued). "Additionally, in basolateral infection, we noticed a relative downregulation of many important genes, when compared to apical infection such as CCR1, CXCL10, integrin α5 (ITGα5) and IFNλ-1, -2 and -3." (PMID 32872518, 2020). "Furthermore, at this time point of infection, Ccr5+/+ and Ccr5−/− mice showed similar CCR1 expression levels in heart tissue and spleen." (PMID 29696014, 2018). "At times early following infection, multiple transcripts encoding proinflammatory molecules were increased, including IL8 (8196-fold), IL1B (1559-fold), oncostatin M (OSM, 799-fold), CCR1 (588-fold), CXCR1 (625-fold), CXCR2 (596-fold), CCL4 (514-fold), and CCL3 (658-fold)." (PMID 25719526, 2015). "For that, we sorted Ccr1lo kidney neutrophils at day 3 and Ccr1high kidney neutrophils at day 9 after infection from Ccr1+/+ Candida-infected mice and compared their potential for degranulation (beta-glucuronidase assay) and oxidative burst (dihydrorhodamine 123 [DHR] assay) ex vivo." (PMID 22916017, 2012). "7/4+ cells were more frequent in Ccr1+/+ kidneys than in Ccr1−/− kidneys post-infection." (PMID 22916017, 2012). "Surprisingly, Ccr1−/− mice infected with Candida had 3-fold better survival than Ccr1+/+ mice at day 14 post-infection (18% versus 56%; P<0.001), an effect maintained through day 28 post-infection (data not shown; P = 0.001), and exhibited less pronounced weight loss (P<0.05)." (PMID 22916017, 2012). "For example, Ccr1 was critical for effective host defense against Toxoplasma gondii, pneumovirus of mice and Aspergillus fumigatus by mediating neutrophil accumulation in the target infection organs." (PMID 22916017, 2012). "Thus, future studies should aim to determine which chemotactic factors, in addition to Ccr1, also mediate neutrophil trafficking from the blood into the kidney late after infection." (PMID 22916017, 2012). "Indeed, Ccr1+/+ kidneys had severe swelling and pallor in gross pathology and exhibited a more pronounced increase in weight post-infection compared to Ccr1−/− kidneys (P = 0.01), a kidney-specific finding not observed in the spleen, liver or brain." (PMID 22916017, 2012). "This time-dependent difference in Ccr1-mediated leukocyte accumulation in the kidney was exclusively accounted for by Ly6cintLy6G+CD11b+ neutrophils, which accumulated in a Ccr1-independent manner until day 6 post-infection, but thereafter were ∼60% decreased in Ccr1−/− kidneys (P≤0.01)." (PMID 22916017, 2012). "Unlike CCR2 and CCR5 deficient mice, 40% of infected CCR1 deficient mice succumbed to infection by 7 dpi." (PMID 19079579, 2008). "Since fungal burden in the kidney has been shown to correlate strongly with mortality in this model, we examined tissue fungal burden in Ccr1+/+ and Ccr1−/− mice at different time-points after infection to determine whether fungal burden differences might account for the difference in survival." (PMID 22916017, 2012). "However, we found that the course of infection in CCR1–/– was similar to that in WT mice." (PMID 21206747, 2010). "Previous studies have shown that BPD-induced damage enhances the function of chemokines and their receptors (e.g., CXCL3, CCR1, CCR2, CCR5), which direct immune cells to sites of infection or injury." (PMID 41345109, 2025). "The observed infiltration of immune cells after infection with swH1N1 agrees with the upregulation of chemotactic factors (AMCF-II, CXCL8/IL8, CXCL2, CXCL10, and CCL20) and their receptors (CCR1 and CXCR2) at the transcriptional level." (PMID 39247193, 2024). "Following extravasation to the site of infection, neutrophils downregulate CXCR2 and upregulate CCR1, 2, and 5, which cumulatively boosts neutrophil ROS production and phagocytic activity." (PMID 39193987, 2024). "The results of quantitative PCR showed that the expression level of CCR5 in NK cells increased and peaked at 48 h, whereas CCR1 levels increased only from 0 to 24 h and declined to baseline at 48 h post MHV-3 infection." (PMID 38017505, 2023).
infection (continued). "Ccr1 has been shown to enhance myelopoiesis and thus promote LT-HSC differentiation into mature myeloid cells upon infection." (PMID 37370129, 2023). "In our previous work, we demonstrated that infection of PB B cells with EBV upregulated two inflammatory chemokine receptors, namely CCR1 and CCR2, and the expression of these chemokine receptors persisted in established LCLs." (PMID 35408790, 2022). "CCR1, 2, 3, 4, and CCL21 and 23 were all decreased in abundance in response to Makona and RESTV infection." (PMID 31689981, 2019). "Studies to investigate the role of specific cytokines and chemokines in the response to infection have shown that these mediators can be beneficial (e.g., IL-6, TNF-α, IL-1, and CXCR1) (62, –, 65), or they can be detrimental (CCR1)." (PMID 29666281, 2018). "The receptors that bind the main chemokine attractants of monocytes (CCR1 for CCL3 and CCR2 for CCL2) that mediate monocyte recruitment to sites of infection were equally expressed on the monocytes of the three groups." (PMID 29116124, 2017). "After infection with ECTV, cells from both mouse strains exhibited reduced percentage of CCR1+ and CCR7+ cells and decreased expression of CCR5, compared to mock-infected cells." (PMID 29312229, 2017). "A reduction of surface expression of chemokine receptors CXCR4 as well as CCR1, CCR2 and CCR5 was observed in monocytes upon their infection with endotheliotropic strains (TB40E and VHLE) and clinical isolates of HCMV." (PMID 27955674, 2016). "Splenic CD4+ YFP+ GFP+ T cells from mice on day 7 of infection were almost universally CXCR3+, whereas they expressed only low levels of CCR1, CCR6, and CXCR6." (PMID 26459508, 2016). "Microarray analysis revealed that the expression of CCR5, CXCR3 and CCR1 and several of their chemokines including CXCL9, CXCL10, CCL2, CCL3 and CCL9 significantly increases in response to infection in CM-affected mice." (PMID 24476686, 2014). "Those mRNAs for CCL2, CCL31, CCL4, CXCL10, CCR1 and CCR5 were significantly increased following infection in both experiments in at least one time-point and CCL5, CCR9 and CXCR4 mRNA were significantly altered in one of the experiments." (PMID 24083897, 2013). "Levels of mRNAs for CCL2, CCL3L1, CCL4, CXCL10, CCR1 and CCR5 were significantly increased in at least one time point following infection in two experiments and CCL5, CCR9 and CXCR4 mRNA were significantly increased in one of the experiments." (PMID 24083897, 2013). "Some other genes such as CCL21, CXCR4, CCR1 and CCR7 exhibited a gradual increase during the infection." (PMID 22905138, 2012). "In addition, in order to determine whether neutrophils obtained from Candida-infected mice respond to Ccr1 ligands, we sorted neutrophils from kidneys of Ccr1+/+ mice at day 9 post-infection and performed chemotaxis assays with recombinant Ccr1 agonists ex vivo." (PMID 22916017, 2012). "Their involvement ranges from serving as co-receptors for cell entry (CCR1 and CCBP2), mediating trans-infection (DARC), activating immune cells (CD97) to inducing viral production from latently infected cells (CSF3R, TNFRSF3 and CD2)." (PMID 20967291, 2010). "This method reproduces reported factors, such as CCR1, CCBP2 and CD97, but also results in a list of promising proteins that likely affect the progression of the infection." (PMID 20967291, 2010). "Neutrophil recruitment in response to PVM infection was diminished five-fold in IFNγ receptor gene-deleted mice, although neutrophils from IFNγR -/- mice expressed transcripts for the CCL3 receptor, CCR1 and responded functionally to CCL3 ex vivo." (PMID 19298652, 2009). "When the vaccine proteins were targeted toward chemokine receptors 1, 3, and 5 (CCR1/3/5) on APC by means of macrophage inflammatory protein 1-alpha (MIP1α) (CCL3), vaccinated mice were broadly protected against infection with H1N1, H3N2, H5N1, and H7N1 influenza viruses." (PMID 41568167, 2026).